MTOR (mechanistic target of rapamycin kinase)
Diseases named in the same sentence as MTOR in open-access papers (continued):
Sharing a sentence is not in itself a finding about the gene and the disease.
cancer (continued). "Studies have reported that multi-drug resistance of chemotherapy often accompanies activation of PI3K/Akt pathway in various cancers, thus we determined the phosphorylation levels of PI3K/Akt/mTOR pathway in xenograft tumor lysates." (PMID 39443476, 2024). "In the signal transduction pathways such as mTOR and PI3K/Akt, mTORC1 further activates RPS6 through phosphorylation of the p70 ribosomal protein S6 kinase to promote protein synthesis for cancer cell growth." (PMID 39621600, 2024). "As an important regulator of oncogenic signaling, FLOT2 participates in the development of cancer via PI3K/AKT/MAPK, PI3K/AKT/mTOR, PI3K/AKT/FOXO and NF-κB signaling pathways." (PMID 38285090, 2024). "CD151 has been demonstrated to promote osteosarcoma pulmonary metastasis, and depletion of CD151 in cancer cells significantly suppressed integrin β1, FAK, p-mTOR, and p70s6 levels as well as Akt, p56 and p38 phosphorylation." (PMID 38389703, 2024). "Recent studies documented that the activation of the PI3K/AKT/mTOR and PI3K/Akt/NF-κB signaling pathways can promote cell proliferation, cancer metabolism, invasion, and migration." (PMID 38167030, 2024). "In conclusion, the present review provides a comprehensive description of how andrographolide regulates the signaling pathways involved in the development of cancer cells, mainly NF-κB, HIF-1, JAK/STAT, PI3K/AKT/mTOR, Wnt/β-catenin and MAPK." (PMID 39301125, 2024). "PRR can exert cellular effects independently of angiotensin II by activating the PI3K/AKT/mammalian target of rapamycin (mTOR) and MAPK/ERK signaling pathways, thereby influencing cancer development and metastasis." (PMID 39684895, 2024). "Given that AKT/mTOR and MAPK pathways are involved in the anti-tumorigenic activity of ASP in cancer, the effect of ASP on the AKT/mTOR and MAPK pathways in EC cells was detected by Western blotting using phosphorylated AMPK, AKT, p42/44, and S6 antibodies." (PMID 39697544, 2024). "In cancer, DUB family members affect multiple tumor‐related signaling pathways, such as NF‐κB, PI3K/Akt/mTOR, Wnt/β‐catenin, Hippo, and TGF‐β, by precisely regulating key molecules like transcription factors and signaling proteins." (PMID 39678489, 2024). "Tannic acid, a gallotannin found in several natural sources, plays a role in various cancer signaling pathways, including the JAK/STAT, RAS/RAF/mTOR, TGF-β1/TGF-β1R axis, VEGF/VEGFR, and CXCL12/CXCR4 axes." (PMID 39830672, 2024). "In terms of malignancies, it kills cancer and cancer-initiating stem cells via activating AMPK pathway, which has a downstream inhibitory effect on cellular proliferation kinases such as PI3/AKT/mTOR." (PMID 39105978, 2024). "Targeting the Akt pathway for cancer treatment is promising due to its frequent activation in different cancers and its crucial role in the PI3K/AKT/mTOR signaling pathway, which governs essential cellular functions." (PMID 38562143, 2024). "Metformin is proven to hinder the proliferation of different types of cancer cells through its impact on glucose metabolism and the phosphatidylinositole-3 kinase-akstrain transforming-mammalian target of rapamycin (PI3K-Akt-mTOR) signaling pathway." (PMID 39429275, 2024). "Activation of mTOR by AKT enhances lipid synthesis and facilitates glucose transportation to cancer cells, thereby enhancing glycolysis." (PMID 39564377, 2024). "As anticipated, P21 treatment significantly increased the abundance of PTEN protein in both cancer cell lines and effectively suppressed phosphorylated-AKT (p-AKT) and phosphorylated-mTOR (p-mTOR) levels, which are downstream signals of PTEN." (PMID 38994018, 2024). "The regulatory mechanism by which paclitaxel induces cancer cell apoptosis has also been well studied, and paclitaxel-induced apoptosis is known to be related to the PI3K/AKT, AMPK, mTOR and JNK pathways." (PMID 39584140, 2024).
cancer (continued). "Our previous studies demonstrated that SH003 treatment induces apoptotic and autophagic cell death of cancer cell lines by targeting PI3K-Akt signaling pathway and their downstream signaling including STAT3 and mTOR." (PMID 38303001, 2024). "The adaptability of cancer cells to PI3K inhibition is demonstrated by their ability to upregulate compensatory pathways such as the MAPK and mTOR pathways." (PMID 38172946, 2024). "The reported pathways which natural products regulate in cancer include NF-kB, inflammation, autophagy, PI3K/AKT/mTOR, MEK-ERK, apoptosis and oxidative stress." (PMID 38633616, 2024). "Its anti-cancer effects are attributed to targeting multiple cellular pathways, including AMP-activated protein kinase (AMPK), AKT/mTOR signaling, and fatty acid synthesis." (PMID 39333445, 2024). "In cancer cells, the eukaryotic translation initiation factor 4E (EIF4E) controlled translation via PI3K/AKT/mTOR and Ras/MAPK/Mnk signaling pathways." (PMID 38361124, 2024). "Here, we describe a novel multiprotein complex (DockTOR) essential for the survival of cancer cells under stress, triggered by the GTPase Cdc42 and a signaling partner Dock7, which includes AKT, mTOR, and the mTOR regulators TSC1, TSC2, and Rheb." (PMID 36711811, 2024). "The binding of angiotensin II to AT1R activates several pathways involved in cancer development, including the PI3K/AKT/mTOR pathway, the RAS/RAF/ERK1/2 pathway, and the JAK/STAT3 pathway." (PMID 39684895, 2024). "Since aberrant signalling of this axis contributes to cancer and other diseases, it is tightly regulated by crosstalk with the PI3K/AKT/mTOR pathway and ERK mediated feedback loops." (PMID 39223665, 2024). "In lung cancer as well, signaling pathways involved in cancer progression such as the mTOR, PI3K/Akt, Wnt/B-catenin are targeted by RSV as a mechanism to reduce the cancer burden." (PMID 38675230, 2024). "Akt phosphorylates various downstream effectors, including mTOR and glycogen synthase kinase 3(GSK-3), contributing to cancer cell growth, proliferation, and survival." (PMID 38297301, 2024). "Multiple molecules interfere with and regulate mTOR, including PI3K and AKT, which are important upstream regulators in cancer." (PMID 38756650, 2024). "OL treatment significantly upregulated genes involved in the cell cycle, tyrosine metabolism, and various neuron-related pathways while downregulating those in the mTOR and MAPK signaling pathways and pathways related to cancer." (PMID 38674064, 2024). "More interestingly, in cancer, AMPK acts through the AMPK/tuberous sclerosis complex (TSC)/mTOR signaling axis to regulate the metabolic switch." (PMID 38255314, 2024). "At the same time, the AMPK, mTOR, and HIF-1 signaling pathways must be given more consideration when developing anti-cancer medications that target purinosomes." (PMID 38746670, 2024). "Recently, however, the discovery of molecules responsible for the pathogenesis of cancer has led to the introduction of targeted pharmacotherapies to SEGA treatment aimed at inhibiting various kinases and signaling pathways, including mTOR kinase." (PMID 39410026, 2024). "Based on our observations, the genes involved in other cancer-related pathways, such as NFκB, VEGF, and mTOR, are all at least partially regulated by EZH2 in HCT116 cells in connection with TKS4." (PMID 38672463, 2024). "Abnormal activation of the PI3K/AKT/mTOR pathway is frequently observed in RCC, which promotes the growth, proliferation, and metastasis of cancer cells." (PMID 39748950, 2024).
cancer (continued). "Fisetin has been proven to regulate the PI3K/AKT/mTOR, Wnt/β-catenin, NF-κB and TRAIL/TRAIL-R pathways to inhibit metastatic spread, autophagy, necroptosis and angiogenesis in different cancer types." (PMID 39168971, 2024). "This study performed in vitro experiments to demonstrate that reducing E2F7 levels has anti-cancer effects on LUAD, achieved by hindering cell growth through the AKT/mTOR signaling pathway and increasing apoptosis signals." (PMID 38760774, 2024). "Moreover, neighbouring cells in the growing cancer mass crosstalk through exosomes (i.e., extracellular double-membrane vesicles carrying regulating non-coding RNA which is introduced between cells), thus further regulating cellular activities, including mTOR regulation." (PMID 38893278, 2024). "The inhibition of mTOR reduces neoangiogenesis and immunosuppression and, thus, would offer a holistic treatment method for KSHV-related cancers." (PMID 39772235, 2024). "With respect to efficacy in preclinical models and in cancer patients, dual inhibition of PI3K and mTOR appears to be superior to the inhibition of either of the targets alone." (PMID 38539472, 2024). "The significant findings from our study strongly suggest that CBD, through its targeting of the PI3K/AKT/mTOR pathway, holds great promise as a therapeutic agent for treating CCA and potentially other cancers." (PMID 39850601, 2024). "IL-6 is frequently upregulated in different cancer types, including OCSCC31, and heightened IL-6 levels can potentially stimulate nodal and distant metastasis through PI3K/AKT/mTOR pathway activation." (PMID 38839809, 2024). "In some cancers, activation of the PI3K/AKT/mTOR signaling pathway resists ferroptosis through controlling the activities of sterol regulatory element-binding proteins 1 (SREBP1) and SCD1." (PMID 38575922, 2024). "The critical role of the PI3K/AKT/mTOR (PAM) pathway in cell survival, proliferation, growth, and apoptosis influences make it a promising drug target in the war against cancer." (PMID 39906126, 2024). "mTOR and ATF4 have been widely studied for their important roles in regulating oncogenic proliferation and cancer cell survival." (PMID 38424194, 2024). "Metformin inhibits mTOR through AMPK-dependent and -independent mechanisms, contributing to its anti-cancer effects." (PMID 38891882, 2024). "The results indicated that ART exerted its anti-cancer effects through multiple pathways, including inhibition of the PI3K/AKT/mTOR pathway, arrest of cell cycle progression, promotion of apoptosis and induction of ROS production." (PMID 39185308, 2024). "Even though several autophagy regulators like mTOR, ULK1, and AMPK have been identified, Beclin-1 is considered a crucial controller of autophagy in cancer." (PMID 39650649, 2024). "Analysis of the function of SMAD3 using GSEA showed that high SMAD3 expression was related to multiple types of cancer including NSCLC, and cancer-related pathways such as PI3K/Akt/mTOR and KRAS." (PMID 38493128, 2024). "FADS2 expression is prognostic in some cancers, and FADS2-mediated sapienate metabolism is regulated by mTOR signaling." (PMID 39337514, 2024). "mTOR inhibitor Sirolimus in combination with Sorafenib and Sunitinib that inhibit VEGFR kinases, were used in clinical trials for different cancer including PDAC." (PMID 38474109, 2024). "Interestingly, patients on mTOR inhibitors, such as sirolimus and everolimus, may exhibit increased radiosensitivity in their cancer cells, which, in turn, would make them more suitable candidates for image-guided hypofractionated or ultra-hypofractionated radiotherapy as a definitive treatment." (PMID 39517998, 2024).
cancer (continued). "In comparison to controls, cancer cells treated with SsnB showed a significant drop in the levels of S1P, PI3K, p-AKT, and p-mTOR." (PMID 39770406, 2024). "Oncogenic signalling pathways that are modified by cholesterol are activated in majority of cancers, such as PI3K-Akt-mTOR, Ras-Raf-MAPK and Hedgehog pathways." (PMID 39243069, 2024). "Other teams showed that increased expression of CRNDE stimulates cancer cells to divide, invade other tissues, and metastasize by activation of the Wnt/ß-catenin, PI3K/AKT/mTOR, Ras/MAPK and Notch1 pathways." (PMID 38673965, 2024). "Anti-cancer SeNPs enhanced the autophagic ability of cancer cells by activating the ROS-mediated JNK pathway and inhibiting the PI3K/Akt/mTOR pathway." (PMID 38999065, 2024). "Metformin inhibits mTOR via AMPK and has been investigated against Panreatic cancer in combination with other chemotherapeutic agents in a phase II trial where the antitumor activity of chemotherapy were not enhanced upon addition of metformin." (PMID 38474109, 2024). "We firstly tested PI3Kα inhibitor Alpelisib and mTOR inhibitor Everolimus, which are two PI3K pathway inhibitors approved for cancer treatment." (PMID 38310289, 2024). "In cancer settings, SGLT-2i has been shown to inhibit glucose uptake, glycolysis, and AKT/mTOR signaling activation, while increasing AMPK expression in thyroid cancer cells, which resulted in decreased tumor cell proliferation and increased apoptosis." (PMID 39201363, 2024). "The duality of CHAC1’s role in cancer likely depends on the specific tumor microenvironment and interactions with other signaling pathways, such as the PI3K/AKT/mTOR or NRF2 pathways." (PMID 39534397, 2024). "In addition to the direct effects of PUFA metabolites (as seen in the case of 4-HNE due to adduct formation), they indirectly change inflammasome activities through mTOR signaling, which may have a significant effect on the modulation of cancer development or progression." (PMID 39290706, 2024). "Quercetin modulates the PI3K/Akt/mTOR, Wnt/β-catenin, and MAPK/ERK1/2 pathways to exert its anticancer effects on cancer cells and tumors." (PMID 39273552, 2024). "It stimulates the PI3K/AKT/mTOR/4E-BP1 signaling pathway, which promotes cancer growth in HCC cells." (PMID 39336774, 2024). "Methylation of m6A is known to be involved in crucial signal transduction pathways in cancer including PI3K/AKT, PTEN/mTOR, and Wnt signaling." (PMID 38848215, 2024). "An important mechanism in cancer formation and progression is the PI3K/AKT/mTOR pathway, which is also called the phosphatidylinositol-3-kinase/AKT/mammalian target of rapamycin pathway." (PMID 39449897, 2024). "Cell signaling pathways in cancer cells, including the PI3K/Akt/mTOR, NF-κB, JAK/STAT, MAPK/ERK, Notch, Wnt, and TGF-β pathways, play a crucial role in drug resistance and metastasis." (PMID 39834817, 2024). "Our study identifies DXS253E as a potentially cancer-promoting gene and suggests its potential application as a therapeutic target for regulating the AKT/mTOR pathway in CRC." (PMID 38890691, 2024). "It has been demonstrated that AA takes part in inhibiting phosphorylation, inducing cell death, and reducing tumor growth and metastasis by influencing important signaling pathways, such as PI3K, Akt, mTOR, p70S6K, and STAT3, in cancer cells." (PMID 38610995, 2024). "Therefore, mTOR inhibitors might be helpful in the treatment of SF3B3 highly expressed cancers." (PMID 38671459, 2024). "Since OTUB2 can promote cancer progression by regulating Hippo, NF-kB and Akt/mTOR pathways, we next investigated the effects of OTUB2-IN-1 on regulating Hippo, NF-κB and Akt/mTOR pathways." (PMID 38167274, 2024). "Beyond its effect on PI3K/Akt/mTOR and Ras/Raf/ERK pathways, linsitinib modulates ABC transporter-mediated multidrug resistance, increasing the accumulation of substrate anti-cancer drugs inside the cells." (PMID 39596005, 2024).
cancer (continued). "It modulated the PI3K/Akt/mTOR pathway, inducing apoptosis and halting the cell cycle in MCF-7 cancer cells." (PMID 38773663, 2024). "Quercetin can influence pathways such as PI3K/Akt/mTOR, Wnt/β-catenin, and MAPK/ERK1/2 to induce apoptosis in cancer cells." (PMID 38648205, 2024). "Its involvement in key pathways like PI3K/Akt/mTOR and its regulation of oncogenes such as MYC and β-catenin further emphasize the importance of context when evaluating FTO’s function in various cancer types." (PMID 39744011, 2024). "Several signaling pathways have been identified as upstream regulators for activation of EMT in cancers, including Wnt, Notch, TGFβ, PI3K/AKT/mTOR, JAK/STAT, and hypoxia/HIF-1α signaling pathways." (PMID 38792011, 2024). "This open-label single-institution phase I trial studied the safety and tolerability of the sapanisertib and metformin in combination with patients with advanced refractory cancer and AKT/mTOR/PI3K alterations." (PMID 38126764, 2024). "Targeting clock genes offers new avenues for cancer treatment, and various targets (e.g., CLK8, mTOR) and drugs (e.g., MLN4924) are under development with ongoing clinical trials." (PMID 38678017, 2024). "Currently, a large number of studies have shown that H2S mediates apoptosis through multiple signaling pathways to participate in cancer occurrence and development, for example, PI3K/Akt/mTOR and MAPK signaling pathways." (PMID 38448410, 2024). "Abnormal activation of PI3K/AKT is known to cause multi-drug resistance by inhibiting apoptosis, promoting cell survival, and enhancing cancer stem cell characteristics, partially through its mediators such as ABC transporters, GSK-3β, and mTOR." (PMID 38562143, 2024). "SFN in combination with chemotherapeutic agents was found to regulate MAPK, Akt/mTOR, NF-κB, Wnt/β-catenin, and STAT3 signaling cascades, thereby inducing the reversal of drug resistance in cancer cells." (PMID 38254735, 2024). "They regulate key pathways such as NF‐κB, PI3K/Akt/mTOR, and MAPK, influencing tumorigenesis and various diseases, including cancer, neurodegenerative diseases, cardiovascular diseases, inflammation, and developmental disorders." (PMID 39678489, 2024). "Some critical pathways related to the PI3K/AKT/mTOR cascades, EMT as well as the cell cycle are regulated by RNAs including miRNAs and noncoding RNAs (ncRNAs), eventually influencing cancer progression." (PMID 38474318, 2024). "As a key protein in PI3K/AKT/mTOR signaling pathway, AKT1 can prevent apoptosis and promote cell survival, which is considered to be a major factor in many types of cancer." (PMID 39224778, 2024). "The EVESOR trial, a phase 1 trial (NCT01932177), focused on the combination treatment of everolimus (an mTOR inhibitor) and sorafenib (a VEGF inhibitor) in 43 cancer patients with various solid tumors, including a subset of 23.2% with CCA." (PMID 38339363, 2024). "In cancer cells, dozens of oncogenic signaling pathways, including the PI3K/Akt and MAPK pathways, lead to hyperactivation of the mTOR signaling pathway." (PMID 39327932, 2024). "The data obtained from the study provide evidence that the mTOR/AKT/PI3K and Ampk/mTOR pathways are involved in the induction of autophagy by CO and PCA in HT-29 cancer cells." (PMID 38952771, 2024). "Among these therapies, metformin has gained attention for its potential anti-cancer effects, primarily through modulation of the AMP-activated protein kinase/mammalian target of rapamycin (AMPK/mTOR) pathway and the induction of autophagy." (PMID 39595655, 2024). "In the present study, we sought to demonstrate the pro-tumor effect of ALDH1A1 by examining the Akt/mTOR signaling pathway, thereby demonstrating the potential feasibility of targeting ALDH1A1 for cancer therapy." (PMID 39107297, 2024).